U3 (Small nucleolar RNA U3 )
Synonyms: LOC124906382
Gene: Small nucleolar RNA gene on chromosome 3 (109,018,909 to 109,019,116, reverse strand). Ensembl gene ENSG00000221633.
Gene Ontology:
Biological process: RNA processing
Cellular component: nucleolus
Homologues: Orthologues: chimpanzee U3 (100% identical), macaque U3 (83% identical). Paralogues in human: SNORD3P1 (77% identical), U3 (76% identical), U3 (75% identical), SNORD3G (75% identical), SNORD3H (74% identical), U3 (74% identical), U3 (73% identical), SNORD3E (72% identical), SNORD3D (72% identical), U3 (72% identical), U3 (71% identical), U3 (70% identical), and 11 more.